SYDE2 (synapse defective Rho GTPase homolog 2)
Description:
GTPase activator for the Rho-type GTPases by converting them to an inactive GDP-bound state.
Synonyms: FLJ13815
Tractability: PROTAC: ubiquitination databases record sites on it.
Gene: Protein-coding gene on chromosome 1 (85,156,851 to 85,201,724, reverse strand). Ensembl gene ENSG00000097096.
Subcellular location (Human Protein Atlas): Golgi apparatus; Nucleoli; Nucleoli rim
Pathways (Reactome):
Signal Transduction: RAC1 GTPase cycle
Gene Ontology:
Molecular function: GTPase activator activity
Biological process: cell migration; activation of GTPase activity; regulation of Ras protein signal transduction; regulation of small GTPase mediated signal transduction; signal transduction
Cellular component: cytosol; synaptic membrane
Genetic constraint (gnomAD): Loss-of-function variants: 58 observed, 72.58 expected, observed/expected ratio (o/e) 0.8, 90% interval 0.65 to 0.99. The upper end of that interval is the gene's LOEUF score, 0.99, which puts it in group 4 of 6, group 1 being the genes least tolerant of losing a copy. Missense variants: 1,208 observed, 1,218.5 expected, observed/expected ratio (o/e) 0.99, 90% interval 0.94 to 1.04. Synonymous variants: 466 observed, 445.97 expected, observed/expected ratio (o/e) 1.04, 90% interval 0.97 to 1.13.
Homologues: Orthologues: chimpanzee SYDE2 (99% identical), macaque SYDE2 (96% identical), dog SYDE2 (82% identical), guinea pig SYDE2 (82% identical), mouse Syde2 (75% identical), pig SYDE2 (75% identical), rat Syde2 (73% identical), rabbit SYDE2 (72% identical), tropical clawed frog syde2 (55% identical), zebrafish SYDE2 (35% identical), Drosophila melanogaster RhoGAP100F (23% identical), Caenorhabditis elegans syd-1 (17% identical). Paralogues in human: SYDE1 (26% identical), ARHGAP35 (17% identical), CHN2 (10% identical), CHN1 (9% identical).
Diseases named in the same sentence as SYDE2 in open-access papers:
SYDE2 is named in the same sentence as 7 diseases in open-access papers, as found by Europe PMC text mining. Sharing a sentence is not in itself a finding about the gene and the disease. The quoted sentences say what the papers report.
breast carcinoma (1 paper, 2014). "Methylated SYDE1 was demonstrated to be significantly associated with the relapse-free survival of patients with breast cancer However, there are currently no studies regarding the implications of SLURP1 and SYDE2 in cervical cancer." (PMID 25109897, 2014).
cervical cancer (1 paper, 2014). A primary or metastatic malignant neoplasm involving the cervix. "Therefore, it was believed that SLURP1 and SYDE2 were potential therapeutic targets for cervical cancer." (PMID 25109897, 2014). "SLURP1 and SYDE2 may be potential therapeutic targets for cervical cancer." (PMID 25109897, 2014). "Furthermore, SLURP1 and SYDE2 may be potential therapeutic targets for cervical cancer." (PMID 25109897, 2014).
Intellectual disability (1 paper, 2022). "The homozygous nonsense C.1544C > G mutation (p.(Ser515*) homo) in Syde2 found in an intellectual disability patient generated a C-terminal truncated transcript devoid of the entire C2 and RhoGAP domain, suggesting a specific role for Syde2 in brain development." (PMID 35279680, 2022). "A clinical study indicated that Syde2 is also a causative gene for intellectual disability." (PMID 35279680, 2022).
systemic lupus erythematosus (1 paper, 2025). An autoimmune multi-organ disease typically associated with vasculopathy and autoantibody production. "TRAT1 shared several overlapping pathways with SYDE2, while ANKRD20A1 primarily affected DNA replication, transcription factor activity, and systemic lupus erythematosus-related processes." (PMID 41200169, 2025).
infection (1 paper, 2021). The state of being infected such as from the introduction of a foreign agent such as serum, vaccine, antigenic substance or organism. "As previously demonstrated, infection causes significant recruitment of SIRT2 to the TSSs of MYLIP, ERRC5, LEF1, SYDE2 and EHHADH but not ARAP2." (PMID 34929015, 2021).
tumor (1 paper, 2014). "SYDE2, a GTPase activator, has also been reported to be a tumor suppressor." (PMID 25109897, 2014).
SYDE2 also shares sentences with these, for which no sentence is quoted: influenza infection (1 paper).